GAP43 (growth associated protein 43)
Diseases named in the same sentence as GAP43 in open-access papers (continued):
Sharing a sentence is not in itself a finding about the gene and the disease.
multiple sclerosis (3 papers, 2013 to 2023). A progressive autoimmune disorder affecting the central nervous system resulting in demyelination. "A recent study described the occurrence of growth-associated protein, GAP43, within axonal swelling of demyelinated fiber tracks in multiple sclerosis." (PMID 24175617, 2013). "A previous study revealed that GAP-43 was reduced in multiple sclerosis and increased when there was remyelination in the lesioned area." (PMID 34086836, 2021).
Obesity (3 papers, 2022 to 2025). Accumulation of substantial excess body fat. "The findings of the study revealed that three plasma proteins (FLT1, GAP43, and SLITRK1) were significantly associated with the risk of obesity and showed a causal relationship." (PMID 40372036, 2025). "The study investigated the causal relationship between three plasma proteins (FLT1, GAP43, and SLITRK1) and obesity, finding that they have a protective effect against obesity risk." (PMID 40372036, 2025). "Our findings of elevated GAP-43 protein levels in overweight and obese individuals suggest a similar pattern, where GAP-43 acts as a mediator of neural responses to the compounding effects of obesity, metabolic imbalance, and mechanical stress." (PMID 40004753, 2025). "Fms-related receptor tyrosine kinase 1 (FLT1), growth-associated protein 43 (GAP43), and SLIT and NTRK-like family member 1 (SLITRK1) plasma proteins had protective effects against obesity." (PMID 40372036, 2025). "It identified three plasma proteins (FLT1, GAP43, and SLITRK1) that were significantly associated with obesity and showed a causal relationship." (PMID 40372036, 2025). "By analyzing genes associated with SNPs causally linked to obesity, gut microbiota, and metabolites, we found that FLT1, GAP43, and SLITRK1 proteins potentially reduce the risk of obesity." (PMID 40372036, 2025). "Other studies examined the effects of high-fat diet-induced obesity on peripheral nerve regeneration and the levels of GAP43, an intrinsic determinant of neuronal development and plasticity, in rats." (PMID 40372036, 2025). "In summary, the study identified three plasma proteins, FLT1, GAP43, and SLITRK1, as having a protective effect against obesity risk." (PMID 40372036, 2025). "FLT1 exhibited a causal relationship with obesity (OR: 0.939, 95% CI: 0.901–0.978, P = 0.002), GAP43 showed a causal relationship with obesity (OR: 0.897, 95% CI: 0.806–0.998, P = 0.046), and SLITRK1 was causally linked to obesity (OR: 0.855, 95% CI: 0.736–0.994, P = 0.041)." (PMID 40372036, 2025). "FLT1, GAP43, and SLITRK1 remained significant under the MR hypothesis and were identified as having a cause-and-effect relationship with obesity according to the IVW method." (PMID 40372036, 2025). "Obesity may reduce the amounts of growth factors (GAP-43) or their effectiveness, which results in a delay in regeneration and recovery." (PMID 36439529, 2022).
thyroid cancer (3 papers, 2019 to 2023). "GAP43 accelerates the malignant development of thyroid cancer cells through epithelial-mesenchymal transition and GAP43 was also reported to be associated with metastasis promotion in lung cancer." (PMID 37205121, 2023). "We discovered that GAP43 was significantly overexpressed in thyroid carcinoma and these results were consistent with that in The Cancer Genome Atlas (TCGA) cohort." (PMID 31568662, 2019). "In our previous study, we selected 19 matched pairs of thyroid carcinoma tissues and nearby non‐cancerous tissues and the outcomes revealed that GAP43 expression was overexpressed in tumour tissues." (PMID 31568662, 2019). "The present study suggested that DIRC3, GAP43, and LRP1B are involved in tumor suppressor activity to inhibit thyroid tumorigenesis, and their mutation may reduce the suppression of thyroid cancer risk." (PMID 33805984, 2021). "GAP43 also promotes thyroid cancer tumorigenesis and tumor progression." (PMID 33805984, 2021). "However, no study has yet demonstrated an association between GAP43 SNPs and thyroid cancer." (PMID 33805984, 2021).
Aphasia (2 papers, 2020 to 2025). An acquired language impairment of some or all of the abilities to produce or comprehend speech and to read or write. "Secondary outcomes: traditional Chinese medicine (TCM) syndrome score scale; western aphasia battery (WAB); water swallow test; Montreal cognitive assessment (MoCA); growth-associated protein-43 (GAP-43); microtubule-associated protein-2 (MAP-2)." (PMID 32358398, 2020).
Arthritis (2 papers, 2015 to 2020). Inflammation of a joint. "Because GAP-43 is thought to indicate processes of structural neuronal plasticity, the present findings suggest that arthritis is associated with neuronal changes in skin innervation remote from the inflamed joint." (PMID 26503622, 2015). "Our findings should stimulate research into the regulation and functional importance of GAP-43 and regenerating nerve fibres in arthritis and chronic, widespread pain." (PMID 26503622, 2015). "The question regarding mechanisms which might be involved in the upregulation of GAP-43 in nerve fibres following arthritis in the skin remote from the joint is intriguing." (PMID 26503622, 2015). "One day after induction of SCW arthritis, 3 genes of this panel were upregulated: NAV1.7 (1.7-fold), ATF3 (1.8-fold), and GAP43 (1.9-fold)." (PMID 32854769, 2020).
astrocytoma (2 papers, 2019 to 2025). "Genetic knock-downs of GAP43 in astrocytomas show abnormal tumor microtube formation and impaired tumor cell dissemination." (PMID 31058089, 2019).
autism (2 papers, 2013 to 2021). Persistent deficits in social interaction and communication and interaction as well as a markedly restricted repertoire of activity and interest as well as repetitive patterns of behavior. "The predictions of our biological model, which is testable, are bolstered by recent genetic studies that have associated single nucleotide polymorphisms in the GAP-43 gene with autism, and identified its extended chromosomal region as an autism risk locus." (PMID 24098278, 2013). "If expression of GAP-43 is also higher in children with autism that would help explain the exuberant branching of axons below ACC in adults." (PMID 24098278, 2013). "In autism, an increase in GAP-43 may persist in adulthood in response to reported inflammation, or due to axon damage." (PMID 24098278, 2013). "In the study of adults with autism, supernumerary branching, and density of thin axons below ACC are associated with increased expression of the Growth Associated Protein 43 (GAP-43)." (PMID 24098278, 2013). "Atypical GAP-43 levels in autism may, therefore, help explain the exuberance of short-range pathways below ACC, which leads to intrinsic overconnectivity in the frontal lobe." (PMID 24098278, 2013). "Therefore, it seems plausible that GAP-43 and related signaling proteins may provide the link between neurological deficits and the extensive immune dysregulation in autism." (PMID 24098278, 2013). "In the brains of adults with autism just below ACC, GAP-43 is expressed in more than double the number of axons than in normal controls." (PMID 24098278, 2013). "In lateral prefrontal areas 9 and 46, neurogenesis and migration are completed much later, when levels of GAP-43 are comparatively low, which helps explain why neither axon branching nor myelination are affected in adults with autism." (PMID 24098278, 2013). "Based on these developmental events, the model predicts that a small increase in GAP-43 in OFC in development can affect myelination but not axon branching, as seen in the brains of adults with autism." (PMID 24098278, 2013).
bipolar disorder (2 papers, 2012 to 2022). A disorder of the brain that causes unusual shifts in mood, energy, activity levels and the ability to carry out day-to-day tasks. "GAP-43 expression is known to be disrupted in bipolar disorder." (PMID 35943710, 2022).
cardiac hypertrophy (2 papers, 2022 to 2025). "The loss of GAP-43 promotes cardiac hypertrophy in newborn GAP-43−/− mice, extending the physiological role of GAP-43 in cardiac muscle." (PMID 40227418, 2025). "Furthermore, the loss of GAP-43 could dysregulate cytokine expression, leading to chronic low-grade inflammation, which is known to promote cardiac hypertrophy like NF-κB or JAK/STAT signaling." (PMID 40227418, 2025). "In GAP-43−/− cardiomyocytes, we found the increased expression of markers of cardiac hypertrophy, Ca2+ alterations, and high mitochondria ROS levels (O2•−) together with increased oxidized functional proteins." (PMID 40227418, 2025). "In this respect, in our experimental condition, we found that GAP-43−/− cardiomyocytes expressed increased levels of cMyH and α-actinin, both markers of cardiac hypertrophy." (PMID 40227418, 2025). "In both tissues, it shares similar locations near the Ca2+ release units, and, interestingly, GAP-43−/− mice develop cardiac hypertrophy." (PMID 40227418, 2025). "Interestingly, GAP-43−/− mice develop cardiac remodeling and hypertrophy, showing an increased cardiac mass index and a thicker ventricular wall and interventricular septum, with a reduced ventricular chamber area." (PMID 40227418, 2025). "Our experiments emphasized that cardiac hypertrophy could be at least a comorbidity factor of sudden death in offspring of GAP-43 knockout mice." (PMID 35201398, 2022).
chronic pancreatitis (2 papers, 2022 to 2025). A chronic inflammatory process causing damage and fibrosis of the pancreatic parenchyma. "High GAP43 expression has been reported in nerves at the site of injury during the early stages of nerve regeneration and nerve fibers in PDAC and chronic pancreatitis compared to normal pancreas." (PMID 40075699, 2025).
endothelial dysfunction (2 papers, 2023 to 2024). In vascular diseases, endothelial dysfunction is a systemic pathological state of the endothelium (the inner lining of blood vessels) and can be broadly defined as an imbalance between vasodilating and vasoconstricting substances produced by (or acting on) the endothelium. "For example, endothelial dysfunction is associated with reduced expression of several presynaptic (e.g., synaptosomal-associated protein-25 (SNAP-25) and growth associated protein-43 (GAP-43)) and postsynaptic (e.g., PSD95) proteins in human AD brains." (PMID 37238700, 2023). "GAP43 expression in ECs has not been widely reported in the literature, and the increased expression of GAP43 in DB ECs may suggest a role in endothelial dysfunction, a hallmark of DB vascular complications." (PMID 39049437, 2024).
epileptic seizures (2 papers, 2017 to 2023). "Therefore, we investigate the expression profiles of neurotrophin-3 and growth-associated protein-43 in children with epileptic seizures, to determine their potential role in epileptic seizures pathogenesis and diagnosis." (PMID 35349008, 2023). "Persistent GAP-43 upregulation is correlated with the early development of epileptogenicity (interictal spikes) and ictogenesis (spontaneous epileptic seizures)." (PMID 29255203, 2017).
hippocampal atrophy (2 papers, 2024 to 2025). "Other studies have demonstrated associations between CSF GAP-43 and total hippocampal atrophy." (PMID 40993981, 2025). "In this study, to further confirm our previous findings that reduced synaptic proteins in EVs are associated with the development of AD, we examined the relationship between concentrations of SNAP25, GAP43, neurogranin, and synaptotagmin 1 and degrees of hippocampal atrophy in patients with AD." (PMID 38528511, 2024). "Despite documented associations between hippocampal volume and episodic memory functions and between hippocampal volume and CSF GAP-43, few studies have examined whether CSF GAP-43 and hippocampal atrophy have additive and/or interactive effects on episodic memory performance." (PMID 40993981, 2025).
Hirschsprung disease (2 papers, 2018 to 2020). Hirschsprung disease (HSCR) is a congenital intestinal motility disorder that is characterized by signs of intestinal obstruction due to the presence of an aganglionic segment of variable extent in the terminal part of the colon. "In a recent study, we have shown that genetic markers within GAL, GAP43 and NRSN1 contribute to the altered HSCR susceptibility, and importantly, the interaction networks among GAP43, NRSN1 and PTCH1 confer an increased risk to Hirschsprung disease." (PMID 32139661, 2020).
inflammatory bowel disease (2 papers, 2021 to 2023). A spectrum of small and large bowel inflammatory diseases of unknown etiology. "GAP-43 has already been used in several intestinal disease models to evaluate neuronal plasticity, such as HD, inflammatory bowel disease (IBD), appendicitis, intestinal neuronal dysplasia, and Nippostrongylus brasiliensis infection." (PMID 33928170, 2021).
lung carcinoma (2 papers, 2019 to 2023). "Data from our study showed that Gfap, Ngfr and Gap43 gene expression is increased in lung cancers, especially in LUSC." (PMID 31921388, 2019). "We observed increased expression of Gap43 and Gfap genes in both lung cancers, whereas Ngfr1 was upregulated only in LUSC cells." (PMID 31921388, 2019).
melanoma (2 papers, 2025). A malignant, usually aggressive tumor composed of atypical, neoplastic melanocytes. "Protrusions of melanoma cells rich in GAP43, MARCKS, and doublecortin travel through white matter and frequently align with oligodendrocyte processes, which are physical guides for the movement of melanoma cells." (PMID 41463339, 2025). "We also looked up various genes classically expressed by Schwann cell precursors or Schwann cells and found that Gap43, Fabp7, Mpz, Dhh, Ngfr, Ncam1, and Mbp were all significantly upregulated in the sparse pigment tumors than in the intradermal melanomas, as was Plp1." (PMID 39804140, 2025).
neurofibroma (2 papers, 2022 to 2023). An intraneural or extraneural neoplasm arising from nerve tissues and neural sheaths. "CSCs in these tumours were somewhat different, the markers of which were PLP, Nestin, P75, GAP43, and Sox10, with GFAP, S100, and GAP43 (as a Schwann cell marker) in differentiated cells, in neurofibroma and MPNST; and Oct4, SOX2, Nanog, MYC, KLF4, CD133, CD44, and CXCR4 in CSCs of schwannoma." (PMID 37370764, 2023).
non-small cell lung carcinoma (2 papers, 2018 to 2021). A group of at least three distinct histological types of lung cancer, including non-small cell squamous cell carcinoma, adenocarcinoma, and large cell carcinoma. "A recent study reported GAP43 as a novel metastasis promoter in non-small cell lung cancer but GAP43 expression is usually highest during critical periods of neural system development." (PMID 34663387, 2021).
ocular hypertension (2 papers, 2021 to 2024). Abnormally high intraocular pressure. "However, the increased levels of RGC-specific transcripts and the presence of the regeneration marker Gap43 indicate a certain degree of spontaneous regeneration occurring in these mice after ocular hypertension begins to subside, a process that starts between 11 and 12 months." (PMID 39456800, 2024). "However, the increased abundance of RGC-specific transcripts and the regeneration marker Gap43 suggests some level of spontaneous regeneration occurring in these mice after ocular hypertension subsides, a process which begins between 11 and 12 months of age in these mice." (PMID 34376637, 2021).
oligodendroglioma (2 papers, 2023). A well-differentiated (WHO grade II), diffusely infiltrating neuroglial tumor, typically located in the cerebral hemispheres. "With regards to LGG, particularly oligodendrogliomas, growth-associated protein 43 (GAP43) regulates microtube outgrowth and is linked to tumor cells’ invasiveness and ability to recolonize the surgical site." (PMID 36831383, 2023). "This explanation accounts for the low expression levels of TTYH1 and GAP43 in oligodendrogliomas compared with those in astrocytomas." (PMID 37173982, 2023).
Pain (2 papers, 2021 to 2022). An unpleasant sensory and emotional experience associated with actual or potential tissue damage, or described in terms of such damage. "Under chronic neuropathic pain- (CNP-) induced allodynia, MWT50 decreased significantly (P < 0.05), and overexpression of MAP2, GAP43, and tau was also observed." (PMID 35915650, 2022).
pancreatic cancer (2 papers, 2021 to 2025). "The presence of nerves by immunodetection with neuronal markers such as S100, protein gene product 9.5 (PGP9.5), and growth-associated protein 43 (GAP-43) was demonstrated in pancreatic cancer (PC) samples, in which larger nerves were associated with worse survival." (PMID 40243726, 2025). "In this study, the presence of nerves and their cross-sectional size were quantified by immunohistochemistry for the neuronal markers S-100, PGP9.5 and GAP-43 in a series of 99 pancreatic cancer cases versus 71 normal adjacent pancreatic tissues." (PMID 33795769, 2021).
peripheral nerve lesion (2 papers, 2006 to 2013). "The expression of GAP-43 mRNA is higher in DRG neurons after peripheral nerve lesions." (PMID 23341911, 2013). "Injection of Corynebacterium extracts into the DRG both enhances the ability of the central axons of DRG cells to regenerate after injury and stimulates upregulation of GAP-43 and c-jun in their cell bodies, thus mimicking some of the effects of a conditioning peripheral nerve lesion." (PMID 16433912, 2006).
primary progressive MS (2 papers, 2019 to 2020). "Low GAP-43 levels in cerebrospinal fluid were associated with a poorer response to treatment of primary progressive multiple sclerosis using fingolimod or alemtuzumab suggesting that GAP-43 is important in mediating its therapeutic effects." (PMID 33015061, 2020). "GAP-43 was measured using an enzyme-linked immunosorbent assay in 105 MS patients (73 RRMS, 12 primary progressive MS, 20 secondary progressive MS) and 23 healthy controls (HCs)." (PMID 31754174, 2019).
retinal degeneration (2 papers, 2023). Degeneration of the retina. "On the other hand, GAP43 aids in photoreceptor survival and delays retinal degeneration, and a deficiency in this protein may potentially impact retinal plasticity in rats." (PMID 38004409, 2023). "In the present study, we found that the intravitreal injection of Hyp-sEVs effectively inhibited photoreceptor apoptosis and ameliorated retinal degeneration mainly through the delivery of GAP43." (PMID 38001463, 2023). "Importantly, the knockdown of GAP43 impaired the therapeutic role of Hyp-sEVs to improve retinal degeneration and inhibit photoreceptor apoptosis in vivo and in vitro, thus confirming that GAP43 is a critical mediator of the repairing effects of Hyp-sEVs on retinal injury." (PMID 38001463, 2023).
schwannoma (2 papers, 2022 to 2023). A benign, usually encapsulated slow growing tumor composed of Schwann cells. "Greater staining of the Antoni A regions would suggest that GAP43 immunoreactivity and protein expression decrease as the spindle cells of schwannomas begin to lose the architecture of Antoni A areas and transition to Antoni B areas." (PMID 35323240, 2022). "Immunoreactivity to CD68, HLA-DR, CD163, CD40 and CD11c (APC phenotype) and markers of neural crest cell (NCC) origin S100, SOX10, NSE and GAP43 in 23 cases of GCTs and 10 cases of Schwannomas were evaluated." (PMID 35323240, 2022). "This gave a patchy appearance to the Schwannoma GAP43 sections." (PMID 35323240, 2022). "Another finding in this report that has not been described is the architecture of schwannoma GAP43 staining." (PMID 35323240, 2022). "GAP43: Both GCT and Schwannoma immunoreactivity was found to be restricted to the cytoplasm." (PMID 35323240, 2022).
synucleinopathies (2 papers, 2023 to 2025). "Presynaptic accumulation of α-synuclein driving synaptic dysfunction instrinsic to synucleinopathies.Widespread reduction in synaptic density found with PET imaging.Some markers of synaptic plasticity (e.g. neurogranin and GAP-43) may correlate with ADNC." (PMID 37387459, 2023).